RPL41P5 (ribosomal protein L41 pseudogene 5)
Synonyms: formerly RPL41L
Gene: Processed pseudogene on chromosome 12 (93,083,598 to 93,083,675, reverse strand). Ensembl gene ENSG00000256393.
Diseases named in the same sentence as RPL41P5 in open-access papers:
RPL41P5 is named in the same sentence as 1 disease in open-access papers, as found by Europe PMC text mining. Sharing a sentence is not in itself a finding about the gene and the disease.
RPL41P5 shares sentences with these, for which no sentence is quoted: cervical cancer (1 paper).